CRP (C-reactive protein)
Diseases named in the same sentence as CRP in open-access papers (continued):
Sharing a sentence is not in itself a finding about the gene and the disease.
ischemic stroke (continued). "It has been shown in a larger cohort in patients with ischemic stroke on the other hand that copeptin is a very strong independent prognostic marker (i.e., independent of age, lesion size, glucose, WBC, CRP and clinical severity on admission) for functional outcome and mortality." (PMID 20504314, 2010). "While other markers of inflammation, such as CRP, fibrinogen and triglycerides, may be elevated in ischemic stroke patients, ESR levels alone may not be sufficient to identify patients with persistent ischemic stroke episodes." (PMID 36766637, 2023). "However, it is not clear whether recurrent ischemic stroke (RIS) is related to H-type hypertension and CRP." (PMID 27164124, 2016).
lung cancer (306 papers, 1995 to 2026). A malignant neoplasm involving the lung. "Prospective studies have linked higher circulating C-reactive protein (CRP), an acute-phase inflammation marker, to higher lung cancer risk in predominantly smoking populations but lower risk in never smokers." (PMID 42094136, 2026). "Multiple studies have established a strong association between elevated CRP levels and poor survival outcomes in lung cancer." (PMID 41226999, 2025). "Conversely, the least deprived socioeconomic group (OR 0.73, 95% CI 0.60–0.90) and normal CRP (OR 0.74, 95% CI 0.52–0.99) were associated with lower lung cancer risk." (PMID 41379769, 2025). "Numerous studies have confirmed the prognostic significance of D-dimer, fibrinogen and CRP in lung cancer, with abnormal levels consistently associated with reduced overall survival." (PMID 41226999, 2025). "The receiver operating characteristic curve analysis was used to review the diagnostic value of serum CRP levels in predicting infection in patients with lung cancer." (PMID 40125102, 2025). "Our patient came in complaining of a month-long history of cough, weight loss, and night sweats, along with elevated ESR and CRP that are suggestive of lung carcinoma, lymphoma, tuberculosis, or systemic vasculitis." (PMID 40718339, 2025). "Several novel serum inflammatory markers, including NLR, PLR, LMR, and C‐reactive protein (CRP), have been shown to predict the risk of tumor recurrence and metastasis, and to assess the survival probability of patients with advanced lung cancer." (PMID 38613182, 2024). "Elevated CRP levels beyond a specific threshold have been associated with unfavorable survival outcomes in various malignancies, including lung cancer." (PMID 38356845, 2024). "For factors associated with lung cancer incidence, some free fatty acids exhibited interactive effects with levels of lymphocytes and C-reactive protein in the bloodstream." (PMID 39275200, 2024). "Mengmeng Ji, through Mendelian randomization, demonstrated a significant correlation between circulating CRP levels and the risk of different histological subtypes of lung cancer." (PMID 39687887, 2024). "Tumor-related inflammation is indicated by elevated levels of inflammatory markers (e.g., C-reactive protein, CRP; interleukin 6, IL-6) and has been linked to poor outcomes in a number of malignancies, including lung cancer." (PMID 39816276, 2024). "While some studies questioned the causal link between elevated CRP and cancer risk, CRP levels remained a predictive marker for lung cancer in current smokers." (PMID 38281018, 2024). "Despite evidence supporting the application of CRP measurements for lung cancer risk stratification, the exact etiological role of CRP in lung cancer requires further clarification." (PMID 37929799, 2023). "Several studies have shown that patients with lung cancer have a higher serum level of CRP than those with benign lung pathologies or healthy people, and those with a high level of CRP have a high risk of developing lung cancer." (PMID 37373957, 2023). "Previous studies have investigated numerous risk factors associated with the co-existence of TB and lung cancer, including smoking, age, gender, inflammatory cytokines, C-reactive protein." (PMID 37817103, 2023). "Elevated CRP levels were strongly associated with lung cancer risk as a chronic inflammation marker and, subsequently, as a lung carcinogenesis biomarker." (PMID 37929799, 2023). "The present study identified several risk factors for NOAF in patients with advanced lung cancer, among which senior age and c-reactive protein level were also predictors for AF among the general population." (PMID 37519821, 2023). "For example, in an 8 year follow-up, elevated C-reactive protein (CRP) was associated with an elevated risk of subsequent lung cancer (hazard ratio = 3.39)." (PMID 35865253, 2022).
lung cancer (continued). "In fact, high serum C-reactive protein levels (CRP) (usually markers of inflammation) are risk factors for the development of lung cancer." (PMID 35525982, 2022). "Our findings support a future longer-term randomized control trial to look at the effects of omega 3 in reducing the incidence of lung cancer in people who are at high risk for lung cancer and have high levels (>2 mg/L) of the inflammatory marker, CRP." (PMID 36532545, 2022). "We also observed a 33% decreased risk of lung cancer for one standard deviation increase in CRP Score 1 (OR: 0.67 [0.47, 0.97]) among those with time to diagnosis over 10 years." (PMID 34915912, 2021). "Our previous study found that CRP/Alb was an independent risk factor for survival in patients with advanced lung cancer and that the CRP/Alb prognostic score ratio was a better predictor than CRP, GPS, mGPS, NLR, PLR, and MLR." (PMID 33495421, 2021). "A meta-analysis published in 2016 suggested that an increased baseline CRP level is associated with a statistically significant worse prognosis in lung cancer patients undergoing lobectomy." (PMID 33628809, 2021). "In the Rotterdam study, baseline CRP levels are associated to chronic inflammation preceding lung cancer, even after subtracting a 5-year latent period, as well as a single nucleotide polymorphism of CRP variation of CRP gene." (PMID 33708198, 2021). "The strongest statistical association appears to be with lung cancer, where elevated CRP is less likely to be due to secondary inflammation from an undiagnosed cancer due to short survival times." (PMID 34926085, 2021). "Previous studies of pre-diagnostic circulating CRP concentration and lung cancer risk (7 cohorts and 3 nested case–control studies) have consistently found a moderate positive association between pre-diagnostic CRP concentrations and lung cancer risk." (PMID 34915912, 2021). "Cigarette smoking is among the main factors associated with lung cancer and has been correlated with higher levels of circulating CRP and differences in tumor immune cell composition." (PMID 32646072, 2020). "Elevated C-reactive protein levels and leukocytes counts have been found to be associated with pulmonary diseases and lung cancer, suggesting an etiologic role of pulmonary inflammation in lung cancer pathophysiology." (PMID 31099339, 2019). "For abnormal laboratory test results, inflammation marker C-reactive protein was most associated with lung cancer (OR=1.771)." (PMID 31099339, 2019). "Previous studies have shown urinary 8-isoprostane levels and CRP to be associated with lung cancer risk." (PMID 31565153, 2019). "The Rotterdam Study demonstrated that high levels (>3 mg/L) of CRP are associated with an increased incidence of lung cancer." (PMID 31487965, 2019). "Using data from a prospective study of lung cancer screening participants from Italy, we already observed that individuals with elevated levels of CRP had a more than three-fold increased risk of overall mortality." (PMID 30150729, 2018). "WBC count, hemoglobin, platelet and CRP levels are associated with poor prognosis in lung cancer, while low hemoglobin and albumin reflect poor nutritional status associated with cachexia in cancer patients." (PMID 30005083, 2018). "The second adjustment for FEV1 loss attenuated the effect of lung cancer on ln (CRP) by 15.2%, as indicated by the change in β for lung cancer (0.197 vs 0.167)." (PMID 28286467, 2017). "The values for ln (CRP) remained significantly higher in patients with lung cancer after adjusting for FEV1 loss." (PMID 28286467, 2017). "For instance, elevated CRP was observed to confer a more than two-fold increased risk of lung cancer." (PMID 27811371, 2016). "CRP, a systemic marker of chronic inflammation, has been found correlated with increased lung cancer risk in many previous studies." (PMID 27811371, 2016).
lung cancer (continued). "Several lines of evidence have revealed that inflammatory biomarkers such as C-reactive protein (CRP) can predict the significant risk of lung cancer." (PMID 27811371, 2016). "The levels of CRP which indicated risk of lung cancer in the study by Hemelrijick and colleagues was over 10 mg/mL." (PMID 26425690, 2015). "Systemic inflammatory markers are also associated with an increased risk of lung cancer and there have been a number of publications in this area particularly in relation to CRP." (PMID 26220864, 2015). "Elevated levels of circulating CRP were associated with increased risk of lung cancer; elevated levels were observed up to 5 years pre-diagnosis." (PMID 26425690, 2015). "Meta-analysis of prospective cohort studies reported an association between CRP and risk of various types of cancers, strong with lung cancer and weak with breast, prostate, and colorectal cancers supporting role of chronic inflammation in carcinogenesis." (PMID 26693355, 2015). "Significant associations were found between the risk of lung cancer and levels of both CRP and serum amyloid A protein." (PMID 26220864, 2015). "Our study found that rs2808630, an intronic SNP within the CRP gene, was significantly linked with lung cancer risk in both allelic and genotypic association analysis of a Chinese population." (PMID 25999661, 2015). "Similar to total SAA, high levels of CRP-SAA were closely associated with the clinical features of lung cancer patients." (PMID 26264146, 2015). "Allin and Nordestgaard demonstrated that individuals with CRP levels in the highest versus the lowest quintile had a 2-fold increased risk of lung cancer." (PMID 26339617, 2015). "Cumulatively, our findings provide evidence that polymorphisms in C-reactive protein and Glypican 5 genes are associated with lung cancer risk, and GKN1 determines chemotherapy response in Chinese population." (PMID 25999661, 2015). "Results for specific cancers remain conflicting except for lung cancer, where a positive association with CRP and leukocytes has been reported." (PMID 26284119, 2015). "Allin and Nordestgaard reported that elevated circulating levels of CRP were associated with an increased risk of lung cancer." (PMID 25360158, 2014). "This relationship is even more questionable in “pre-clinical disease”: a study on a large cohort showed that increased CRP levels in cancer-free subjects were associated with a higher risk of lung cancer occurrence." (PMID 25238252, 2014). "Recently Shiels and colleagues reported that elevated circulating inflammation markers are associated with lung cancer risk, with CRP having the highest risk related odds ratio." (PMID 25114662, 2014). "All studies on the association of CRP with lung cancer risk showed an positive association, which was statistically significant in 5 studies." (PMID 22912790, 2012). "Our summary estimate of CRP and lung cancer risk were similar to that of another recent meta-analysis." (PMID 22912790, 2012). "In summary, findings from this meta-analysis indicated that CRP was associated with increased risk of lung cancer, especially among men." (PMID 22912790, 2012). "The complementary and mutually independent associations between CRP and lung cancer, respectively, YKL-40 and gastrointestinal cancer are intriguing." (PMID 22095223, 2012). "The positive association between CRP and lung cancer risk is supported by the prospective design of the 10 studies." (PMID 22912790, 2012). "We identified 21 potentially relevant articles concerning CRP or IL-6 in relation to lung cancer risk." (PMID 22912790, 2012). "Overall, we identified a moderate positive association between pre-diagnostic CRP concentrations and lung cancer risk." (PMID 22912790, 2012). "Subsequently, several epidemiologic studies with large sample sizes or long-term follow-up have been performed regarding CRP, IL-6 and the risk of lung cancer." (PMID 22912790, 2012).
lung cancer (continued). "Elevated YKL-40 levels are associated with increased risk of gastrointestinal cancer, independently of CRP levels, whereas elevated CRP levels are associated with increased risk of lung cancer, independently of YKL-40 levels." (PMID 22095223, 2012). "A meta-analysis published in 2009 found that a natural log (ln) unit increase in CRP was associated with a 1.32-fold increase (95% confidence interval [CI] 1.08–1.61) in lung cancer risk, however, significant heterogeneity was found." (PMID 22912790, 2012). "During the last decade, several epidemiologic studies have evaluated the associations between CRP, IL-6 and lung cancer risk." (PMID 22912790, 2012). "This meta-analysis which included 6 studies with only 551 cases reported that a unit increase in ln CRP was associated with 32% increase in lung cancer risk." (PMID 22912790, 2012). "Elevated CRP levels have been shown in prospective studies to be associated with greater decline in lung function and elevated lung cancer risk after adjustment for smoking." (PMID 21304900, 2011). "Recently the combination of C-reactive protein and albumin, termed the mGPS, was shown to be associated in a similar manner in patients with lung cancer and predict cancer-specific survival in a number of operable and inoperable cancers." (PMID 20717110, 2010). "Recent evidence has associated CRP elevation using static measurements with progression of melanoma, ovarian, colorectal and lung cancer, and CRP has been used to detect recurrence of cancer after surgery in certain situations." (PMID 19948067, 2009). "Similarly, other studies involving patients with gastric, colorectal, pancreatic, and lung cancers have indicated that a lower mGPS, also based on serum CRP and albumin levels, was associated with a better treatment response." (PMID 40627291, 2025). "Lung cancer patients often exhibit elevated baseline inflammatory markers (e.g., IL-6, C-reactive protein) due to tumor-associated inflammation, which may amplify postoperative inflammatory responses and increase POAF risk." (PMID 40421295, 2025). "Common variant; lung cancer; C-reactive protein; causal relationship." (PMID 40797480, 2025). "Inflammatory states such as increased CRP levels are associated with an increased lung cancer risk." (PMID 40224371, 2025). "CRP is a pre-diagnostic marker of lung cancer in current smokers and in small cell lung cancers." (PMID 40558585, 2025). "The association between brisk walking pace and lung cancer was also significantly mediated, albeit to a lesser extent, by CRP, WBC count, total cholesterol, and LDL cholesterol, with proportions of mediation ranged from 2.0 to 2.3% and a combined mediated proportion of 5.9% (4.5–7.9%)." (PMID 40275681, 2025). "This study aims to explore whether targeted therapy affects cognitive function in patients with advanced lung cancer and to explore the association between cognitive function, the inflammatory biomarker C-reactive protein, and psychological stress." (PMID 40966684, 2025). "After adjustment of gender, targeted therapy and anti-angiogenic therapy, the incidence of COVID-19 pneumonia remained positively associated only with serum CRP (OR = 9.8, 95%CI: 2.2, 43.8; P = .003) and was negatively associated with lung cancer (OR = 0.3, 95%CI: 0.1, 0.7; P = .006)." (PMID 38215120, 2024). "Moreover, CRP is associated with a poor clinical outcome for various cancers treated with immune-checkpoint inhibitors (ICIs), including melanoma and non–small cell lung cancer (NSCLC)." (PMID 38717686, 2024). "In addition, many correlation studies on CRP and lung cancer have demonstrated that elevated CRP levels are associated with increased lung cancer risk, and it has been suggested that CRP is a pre-diagnostic marker for lung cancer." (PMID 37929799, 2023). "High CRP levels have also been linked to a worse prognosis in patients with lung cancer." (PMID 37444523, 2023).